S100B (S100 calcium binding protein B)
Diseases named in the same sentence as S100B in open-access papers (continued):
Sharing a sentence is not in itself a finding about the gene and the disease.
meningitis (7 papers, 2009 to 2024). A disorder characterized by acute inflammation of the meninges of the brain and/or spinal cord. "CSF S100B is a marker of damage in purulent meningitis and has been implicated as useful for prognosis." (PMID 38115295, 2023). "This distinction suggests that S100B may be an important biomarker in suspected cases of meningitis and in the diagnostic differentiation of TBM from other infectious meningitis cases." (PMID 38115295, 2023). "S100B had the highest contribution to the differentiation of meningitis groups from the healthy control group." (PMID 38115295, 2023). "The S100B protein was found to be effective in discriminating between healthy controls and patients with meningitis and between different types of meningitis." (PMID 38115295, 2023). "A heat map was created to visualize the concentrations of DEFA1, GFAP, ALOX5, and S100B in the meningitis and healthy control groups." (PMID 38115295, 2023). "The parameter that had the greatest additive to the discrimination of the meningitis groups from the control group was S100B, and S100B levels were significantly higher in the TBM group than in the other groups." (PMID 38115295, 2023). "Here, the levels of ALOX5, S100B, DEFA1, and GFAP in the CSF of patients with meningitis caused by different infectious agents were compared to those of healthy controls." (PMID 38115295, 2023). "It should be pointed out that NSE values in the CSF were significantly higher in patients with meningoencephalitis in comparison to individuals with meningitis and controls, while S100B levels were similar in TBE and the control group." (PMID 34638953, 2021). "A positive correlation was identified between CSF-S-100B and CSF-LPO and between S-100B ratio and the severity of meningitis as indicated by PGCS." (PMID 19814795, 2009). "DEFA1, GFAP, ALOX5, and S100B successfully distinguished patients with meningitis from controls." (PMID 38115295, 2023). "S100B plays a particularly an important role in distinguishing TBM from other types of meningitis." (PMID 38115295, 2023). "In our assessment, levels of HBP and NGAL in CSF, as well as of S100B in the blood of patients suspect of meningitis can provide fast confirmation of bacterial etiology and inform the decision to administer antibiotic therapy swiftly, before the results of conventional cultures are available." (PMID 35740230, 2022). "According to the heat map, ALOX5, S100B, DEFA1, and GFAP levels were partially increased in the meningitis group versus controls." (PMID 38115295, 2023). "In both the diagnosis of infectious meningitis groups and in the separation of meningitis species, the VIP score was determined to be the highest S100B." (PMID 38115295, 2023). "ROC curve analysis was performed to differentiate the variation in ALOX5, S100B, DEFA1, and GFAP between groups to distinguish meningitis patients from healthy individuals and from different types of meningitis." (PMID 38115295, 2023). "Comparison of CSF levels of ALOX5, S100B, DEFA1, GFAP in the groups with infectious meningitis and in the healthy control groups." (PMID 38115295, 2023). "The CSF and blood levels of HBP, NGAL, S100B, and NSE of 81 patients with meningitis were measured and analyzed comparatively." (PMID 35740230, 2022). "This is, to our knowledge, the first study investigating the levels of HBP, NGAL, S100B, and NSE in both the blood and the CSF of patients diagnosed with meningitis via conventional means." (PMID 35740230, 2022). "S100B, NSE, and NPY were significantly elevated in the acute miliary tuberculosis with secondary tubercular meningitis vs. other groups." (PMID 33115334, 2021). "Compared to healthy children, serum albumin was lower, while serum S-100B (p < 0.05), NO, LPO, total thiol, SOD were higher in patients with meningitis." (PMID 19814795, 2009).
meningitis (continued). "This study showed that the parameters ALOX5, S100B, DEFA1, and GFAP could discriminate between meningitis patients and healthy controls, although with varying degrees of reliability." (PMID 38115295, 2023). "The S100B levels decreased over time, probably since these were taken further from the disease onset compared to S100B levels sampled in TBI patients, with a half-life of approx. 30 minutes, albeit the kinetics of S100B in serum of meningitis patients is not fully understood." (PMID 27019200, 2016). "In addition, several studies have found that the levels of NSE, S100B, and Neuropeptide Y (NPY) in the serum and cerebrospinal fluid of children with acute miliary TB secondary to TB meningitis are significantly higher than those of children with acute miliary TB or meningitis alone." (PMID 38822291, 2024).
renal failure (7 papers, 2008 to 2020). "Patients with renal failure have higher baseline S100B levels compared to healthy controls, which should be taken into consideration when assessing S100B in these patients." (PMID 27957604, 2017). "This is unlikely since common sources of S100B release such as renal failure and surgical tissue injury were either excluded or avoided." (PMID 20374626, 2010). "Although S100B is eliminated by the kidneys, in-vivo studies have not shown a detectable rise in S100B concentration in renal failure, probably due to its estimated 2 hour biological half life." (PMID 18803814, 2008). "Some of our patients had acute renal failure and haemofiltration, but neither renal failure nor haemofiltration influences S-100β levels." (PMID 18457586, 2008). "Transient elevation of S100B could accompany an increase in BBB permeability without brain injury or result from surgical tissue injury or renal failure." (PMID 32382007, 2020).
atrial fibrillation (6 papers, 2013 to 2024). A disorder characterized by an electrocardiographic finding of a supraventricular arrhythmia characterized by the replacement of consistent P waves by rapid oscillations or fibrillatory waves that vary in size, shape and timing and are accompanied by an irregular ventricular response. "After catheter ablation of atrial fibrillation, cardiac glial cells release S100B, which acts as a neurotrophic substance." (PMID 37217870, 2023). "Several studies mentioned the increase of serum S100B levels after cardiac interventions such as catheter ablation for atrial fibrillation, cardiopulmonary bypass or other cardiac surgical interventions such as vascular by-pass." (PMID 34821692, 2021). "However, PAI-1 did not remain an independent variable in the best diagnostic model, which consisted of age, face- arm- speech test (FAST), atrial fibrillation, and three other serum markers (protein S100B, MMP-9 and IL-6)." (PMID 39001884, 2024). "Baseline data analysis revealed that several key indicators, including DBP, atrial fibrillation incidents, NIHSS score, d-D, hs-CRP, NLR, SIRI, SII, NT-proBNP, as well as the S100-β, were significantly elevated in the POCD group compared to the non-POCD group." (PMID 39711844, 2024). "Furthermore, patients with higher S100B release had lower rates of atrial fibrillation relapse during follow-up, as S100B may contribute to the sprouting of local neurons, diminishing action potential firing by reducing neuronal electrical activity, and increasing neurite growth." (PMID 34821692, 2021). "In addition, myofibroblast proliferation is induced by secreted vascular endothelial growth factor (VEGF) by cardiomyocytes in response to S100B via RAGE ligation, which may help promote tissue damage repair and adaptive remodeling in patients with chronic atrial fibrillation." (PMID 37217870, 2023).
celiac disease (6 papers, 2014 to 2023). An autoimmune genetic disorder with an unknown pattern of inheritance that primarily affects the digestive tract. "S100β is produced in large amounts in the duodena of patients with celiac disease, where it plays an important role in NO production, also leading to IEB damage and intestinal inflammation." (PMID 37779161, 2023).
cerebral edema (6 papers, 2015 to 2024). "One prior study found an association between early S100B protein serum levels and life-threatening cerebral edema, which supports our findings." (PMID 37752283, 2023). "There are a few controversial studies showing that S100B can be used as a marker for cerebral edema in pediatric DKA." (PMID 31067852, 2019). "It was reported that S100B levels were not raised in subclinical cerebral edema in children with DKA." (PMID 31067852, 2019).
colon carcinoma (6 papers, 2019 to 2022). "The findings of this study show that increased S100B protein levels are correlated with significant increase in proliferation and migration of human colon cancer cell in vitro." (PMID 34035661, 2021). "Here, we demonstrated that increasing concentrations of S100B protein are accompanied by a marked increase in proliferation, migration and invasion rates in an in vitro model of human colon cancer." (PMID 31266264, 2019). "Additionally, Kaplan-Meier survival analysis indicated that colon cancer patients in the GFAP/S100B-HIGH group had a shorter overall survival time than those in the GFAP/S100B-LOW group." (PMID 36522730, 2022). "To date, a possible pro-angiogenic effect of S100B in colon cancer cells and its underlying molecular mechanism(s) have not been investigated yet." (PMID 31266264, 2019). "Although hampered by their in vitro nature, these results support that the selective targeting of S100B protein might represent an interesting innovative approach in colon cancer therapy." (PMID 31266264, 2019). "Although further in vivo studies are required to confirm these in vitro preliminary results, S100B targeting might represent a promising therapeutic approach against colon cancer." (PMID 31266264, 2019).
hematoma (6 papers, 2017 to 2025). A hematoma is a collection of blood from a vascular structure into an extravascular space. "Serum levels rise after ICH, and S100B levels have a positive correlation with hematoma volume and can predict early neurologic deterioration and unfavorable outcomes 3 months after acute spontaneous ICH45." (PMID 28361971, 2017). "Our results align with prior research indicating elevated levels of APP, S100β, and NFL proteins in regions affected by hematomas." (PMID 39981435, 2025). "We found that Soft robotic hands therapy benefited in hand function in patients with ICH and hematoma volume, FMA-WH score admission, S100B, and NfL were all significant predictors for poor motor function of patients with ICH." (PMID 36068493, 2022). "We also found that soft robotic hands therapy benefited in hand function in patients with ICH and hematoma volume, FMA-WH score admission, S100B, and NfL were all significant predictors for poor motor function of patients with ICH." (PMID 36068493, 2022). "The multivariate logistic regression showed that hematoma volume (OR = 1.47, p = 0.007), FMA-WH score admission (OR = 0.78, p = 0.02), S100B (OR = 1.32, p = 0.04), and NfL (OR = 1.24, p = 0.003) were all significant predictors of poor motor function." (PMID 36068493, 2022). "Using the multivariate logistic regression, we found that hematoma volume (OR = 1.47, p = 0.007), FMA-WH score at admission (OR = 0.78, p = 0.02), S100B (OR = 1.32, p = 0.04), and NfL (OR = 1.24, p = 0.003) were all significant predictors of poor motor function." (PMID 36068493, 2022). "We found that DBP (OR = 1.03, p = 0.03), hematoma volume (OR = 1.48, p = 0.001), FMA-WH score admission (OR = 0.67, p < 0.001), CAF (OR = 8.18, p < 0.001), S100B (OR = 1.04, p < 0.001), and NfL (OR = 1.17, p < 0.001) were all significant predictors of poor motor function." (PMID 36068493, 2022). "In conclusion, HBO improves consciousness, cognitive function, and prognosis in patients with severe or moderate TBI through decreasing TBI-induced hematoma volumes, promoting the recovery of EEG rhythms, and modulating the expression of serum NSE, S100β, GFAP, BDNF, NGF, and VEGF." (PMID 36034283, 2022). "HBO may be an effective treatment for patients with TBI to improve consciousness, cognitive function and prognosis through decreasing TBI-induced hematoma volumes, promoting the recovery of EEG rhythm, and modulating the expression of serum NSE, S100β, GFAP, BDNF, NGF, and VEGF." (PMID 36034283, 2022).
intracerebral hemorrhage (6 papers, 2016 to 2025). A cerebrovascular disorder characterized by bleeding into one or both cerebral hemispheres including the basal ganglia and the cerebral cortex. "In some central nervous system disorders, such as intracerebral haemorrhage and ischaemia–reperfusion injury, the increase in serum S100B levels was consistently detected by biochemical analyses of S100B levels in the brain." (PMID 33006697, 2021). "Based on these facts, we hypothesized that higher S100β levels are related to global ischemic injury after initial intracerebral hemorrhage that subsequently lead to neurological decline and poorer outcome." (PMID 39970158, 2025). "Levels of S100B have also been shown to be increased in patients with transient ischemic attacks (TIA) and intracerebral hemorrhage when compared with patients with IS or healthy controls, potentially being able to discriminate IS from TIA and ICH." (PMID 34685473, 2021).
manic episodes (6 papers, 2009 to 2023). "On the other hand, Tsai and Huang (2017) found that S100B levels decreased while treating bipolar patients presenting manic episodes." (PMID 35448545, 2022). "Therefore, we assumed that the S100B level would significantly change with successful treatment, as shown in the study on patients with manic episodes." (PMID 35448545, 2022). "Increased S100β levels in serum of patients with manic episodes." (PMID 34025481, 2021).
mental disorder (6 papers, 2010 to 2025). A disease that has its basis in the disruption of mental process. "Logistic regression revealed that craniocerebral injury severity, family satisfaction, and serum levels of S100-β and GFAP were significant risk factors for post-traumatic mental disorders (p < 0.05)." (PMID 39801405, 2025). "The diagnostic value of MMP-9, S100-β, and GFAP in detectingpost-traumatic mental disorders is substantial, with a significant correlationobserved among the biomarkers." (PMID 39801405, 2025). "Therefore, future mechanistic studies on the effect of S100B on this group of mental disorders are warranted." (PMID 37225692, 2023). "Future studies could compare levels of S100B in plasma and in CSF to investigate the potential contribution of blood–brain barrier disruption to stress-related mental disorders." (PMID 35585111, 2022). "It is therefore useful to investigate whether any raised levels of S100B in patients with stress-related mental disorders are correlated with increased levels of astrocyte-derived EVs in those patients." (PMID 35585111, 2022). "Serum levels of MMP-9, S100-β, and GFAP were significantly elevated in the post-traumatic mental disorder group compared to the simple traumatic brain injury group (p < 0.001)." (PMID 39801405, 2025). "Serum levels of MMP-9, S100-β, and GFAP hold significant promise for thefuture diagnosis and management of post-traumatic mental disorders." (PMID 39801405, 2025). "Spearman correlation analysis of serum MMP-9, S100-β,GFAP, and the incidence of post-traumatic mental disorders." (PMID 39801405, 2025). "Spearman correlation analysis showed that serum MMP-9, S100-β and GFAP were significantly positively correlated with the incidence of post-traumatic mental disorders (p < 0.001)." (PMID 39801405, 2025).
metabolic syndrome (6 papers, 2010 to 2024). A cluster of metabolic risk factors for CARDIOVASCULAR DISEASES and TYPE 2 DIABETES MELLITUS. "In metabolic syndrome, S100B levels are higher than in healthy individuals." (PMID 39519343, 2024).
ovarian carcinoma (6 papers, 2018 to 2022). A malignant neoplasm originating from the surface ovarian epithelium. "Our study proposed that circ_MUC16 aggravated ovarian cancer development by reinforcing S100B expression via competitively binding to miR-1182." (PMID 34837947, 2021). "Previous studies showed that the expression of S100B was strikingly enhanced in ovarian cancer tissues, and S100B overexpression promoted ovarian cancer stem cell chemoresistance and stemness." (PMID 34837947, 2021). "Circ_MUC16 overexpression alleviated the effects of Propofol to promote the aggressive behaviors of ovarian cancer by targeting the miR-1182/S100B network." (PMID 34837947, 2021). "Consistent with these views, our data showed that S100B overexpression restored proliferation, migration and invasion in ovarian cancer cells that were suppressed by miR-1182 restoration, suggesting that S100B promoted ovarian cancer malignant development." (PMID 34837947, 2021). "In summary, circ_MUC16 attenuates the effects of Propofol to promote the development of ovarian cancer by mediating the miR-1182/S100B signaling pathway." (PMID 34837947, 2021). "Nevertheless, among others, S100A3, S100A10, and S100B were identified to be related to drug resistance in ovarian cancer." (PMID 32722137, 2020). "Besides, we uncovered the interactions among circ_MUC16, miR-1182 and S100B, aiming to provide a potential mechanism of circ_MUC16 in Propofol-mediated ovarian cancer progression." (PMID 34837947, 2021).
transient ischemic attack (6 papers, 2014 to 2024). A brief attack (from a few minutes to an hour) of cerebral dysfunction of vascular origin, with no persistent neurological deficit. "Lower plasma concentrations of S100β have been reported in only one study, in patients with transient ischaemic attack (TIA) or normal brain CT on admission in comparison with individuals with neurological deficits or abnormal brain imaging displaying cortical infarcts." (PMID 25029344, 2014). "However, the S100B-mediated inflammatory inhibitors exert neuroprotective effects against cerebral I/R injury by reducing oxidative stress and suppressing the inflammatory response after transient cerebral ischemia." (PMID 24626220, 2014).
vascular dementia (6 papers, 2019 to 2025). A degenerative vascular disorder affecting the brain. "Additionally, SCE caused a reduction in S100B levels in brain regions associated with vascular dementia." (PMID 36618764, 2022). "In patients with AD and vascular dementia, parallel overexpression of S100B and the proinflammatory cytokine IL-1 has been observed, which plays a significant role in the pathogenesis of neuropathological changes." (PMID 41516246, 2025). "An earlier study reported higher S100B in vascular dementia than vascular MCI in correlation with clinical impairments, although they did not compare values with healthy controls." (PMID 35910248, 2022). "Levada and Trailin (2012) found increased serum S100B in vascular dementia compared to its pre-stage, vascular MCI." (PMID 35910248, 2022).